ESR1 (estrogen receptor 1)
Diseases named in the same sentence as ESR1 in open-access papers (continued):
Sharing a sentence is not in itself a finding about the gene and the disease.
breast cancer (continued). "Immunoblotting results identifying the suppression of miR-129 exerted on ESR1 and its downstream cyclin d1 in breast cancer stem-like cells." (PMID 29262559, 2017). "The NRs in the cancer group include RARA (acute promyelocytic leukemia), NR1H4 (hepatocellular carcinoma), ESR1 (breast cancer), and AR (prostate cancer)." (PMID 29065888, 2017). "This factor is involved in ESR1-mediated transcription (required for ESR1 binding to the NKX2-1 promoter in breast cancer cells), of the RPRM promoter, needed for estrogen-induced repression in these cells." (PMID 29290962, 2017). "Enforced miR-129 reduced the stem cells number of breast cancer, which was achieved by post-translational regulation of ESR1 level." (PMID 29262559, 2017). "In tumor-distant tissues from breast cancer patients, the methylation status of ESR1 was negatively correlated with the age of the patients at diagnosis (r = −0.673, p = 0.002)." (PMID 28403857, 2017). "To explore the clinical relevance of the effect of GLI1 on ERα signaling and breast cancer, we examined the expression of GLI1, ESR1 (the gene encoding ERα) and known ERα target genes in a dataset of breast cancer samples from 286 individuals." (PMID 27689403, 2016). "This also confirmed our previous results showing that expression of the receptor coding gene ESR1 in ERα− breast cancer cells increased their resistance to PAC." (PMID 27465411, 2016). "Postmenopausal Chinese patients with breast cancer carrying an ESR1 rs2234693 CC genotype or rs9340799 AA genotype had an increased risk of AI-related musculoskeletal AEs." (PMID 27825388, 2016). "Most women with primary breast cancers that express estrogen receptor alpha (ER or ESR1) are treated with endocrine therapies including the anti-estrogen tamoxifen, but resistance to these anti-endocrine therapies often develops." (PMID 26884724, 2016). "An association with an increased risk of developing breast cancer was found in the SNPs localized in the CASP8, TNRC9 and ESR1 genes." (PMID 26770289, 2016). "Only the ESR1 (rs2046210), TERT (rs2242652) and two 19p13.1 (rs8170; rs56069439) loci had genome-wide significant associations with breast cancer risk for BRCA1 mutation carriers alone." (PMID 27117709, 2016). "In 59 breast cancer cell lines, HLA gene expression was inversely correlated with ESR1 expression and positively correlated with expression of IFN associated genes." (PMID 27121061, 2016). "Fusion transcripts involving the same intron of ESR1 are recurrent in breast cancer, and there is evidence they have important functional consequences, largely conferred by the C-terminally truncated estrogen receptor." (PMID 27498871, 2016). "In this study, we have conducted a genome-wide association study (GWAS) to identify genetic risk factors associated with mammary tumour predisposition in the ESS breed in addition to BRCA1/2 and ESR1." (PMID 27158822, 2016). "This is consistent with persistent dependence of endocrine-resistant breast cancer cells on ESR1 expression and activity." (PMID 27612429, 2016). "We have previously shown that the known human breast cancer genes BRCA1, BRCA2 and ESR1 are associated with CMT in ESS dogs overlapping with this cohort, although not as strongly as the risk factors identified in this GWAS study." (PMID 27158822, 2016).
breast cancer (continued). "These important drug targets in breast cancer, ESR1, PGR, HER2, EGFR and AR have a high similarity in mRNA and protein variation in both tumors and cell lines." (PMID 27556158, 2016). "As expected, considering that the seed gene ESR1 is related to breast cancer, both at 0 and 4 h the graphs are enriched in SNPs associated to breast cancer, with p < 9.3e−20 and p < 1.74e−27 respectively." (PMID 27895661, 2016). "These “repressed” genes include ESR1 (gene encoding ERα), ERBB2, GATA3, and ZNF217 —all critical genes to the etiology of breast cancer." (PMID 27539783, 2016). "Unsurprisingly, the protein products of ERBB2 and ESR1 are targets of drug and hormone therapy for breast cancer." (PMID 27112211, 2016). "So, particularly for key breast-cancer genes, such as ESR1, isoform-level data are more informative than gene-level data, allowing us to determine how variants contribute to the hormone dependence and treatment response of the tumor." (PMID 27634900, 2016). "Based on gene expression profiles in 2000 breast cancers, our previous network analysis using ARACNe defined a regulon (set of potential target genes) for ESR1." (PMID 27236187, 2016). "In contrast, TCGA breast cancers exhibit ESR1 truncations on DNA-level less than half as often (7 of 1080; 0.65%) as observed in endometrial cancer and had increased expression of exons 1–2, but not of the full DNA-binding domain." (PMID 27160768, 2016). "Data form Adams and colleagues demonstrated that miR-206 suppresses ESR1 mRNA and protein level in breast cancer cell lines." (PMID 27834829, 2016). "Nevertheless, important drug targets in breast cancer, such as ESR1, PGR, HER2, EGFR and AR possess highly correlated in mRNA-protein expression both in tumors and cell lines." (PMID 27556158, 2016). "COPS5 gene is located at the chromosome 8q13 which is amplified (copy number (CN)>6) in about 9% (70/774) of the ERα+ breast cancer (Log2 ESR1 expression>5)." (PMID 27375289, 2016). "We further validated binding of the TFs GATA3, FOXA1 and ESR1 to the enhancers activated in breast cancers using publicly available ChIP-seq data." (PMID 27833659, 2016). "It has been shown that the 5′ region of the ESR1 gene is methylated in ER− breast cancer cell lines." (PMID 27260000, 2016). "Expression of CCN5 is highly upregulated by estrogen, especially in MCF-7 breast cancer lines that express estrogen receptor alpha (ESR1), making it an oncogene." (PMID 26395334, 2015). "PreM breast cancer involved hyper-methylated ESR1, lower levels of ESR1 gene expression, and lower levels of ER protein expression." (PMID 26251034, 2015). "A heatmap highlights the hypomethylated status of the ESR1-enhancer sites in luminal A disease relative to normal breast tissue and the other breast cancer subtypes." (PMID 26169690, 2015). "ESR1 is a member of the nuclear receptor family of ligand-activated TFs and is involved in the development and progression of breast cancer." (PMID 26099425, 2015). "Our results support a model whereby ESR1-responsive enhancer DNA methylation is a fundamental unifying characteristic that defines endocrine sensitivity in breast cancer." (PMID 26169690, 2015). "On the other hand, there is a large collection of genes mutated in <3% of breast cancers, some of which are known driver genes or are targeted by mutations that have been associated with treatment resistance such as HER2 and ESR1." (PMID 25994018, 2015). "Cumulatively, these novel insights highlight the potential of ESR1-responsive enhancer methylation to both predict ESR1-positive disease and stratify ESR1-positive breast cancer patients as responders to endocrine therapy." (PMID 26169690, 2015). "DNA methylation variability regions (MVRs) across the oestrogen receptor alpha (ESR1) gene have been identified in peripheral blood cells from breast cancer patients and healthy individuals." (PMID 25927974, 2015).
breast cancer (continued). "Among the ten candidate modulator genes, the positive control ESR1 and two genes with essential functions in breast cancer were found modulating the most numbers of gene pairs." (PMID 26100352, 2015). "The expression pattern for Human Epidermal Growth Factor Receptor 2 (HER2/neu) and the estrogen receptor alpha (ESR1), known breast cancer markers, were used as controls." (PMID 25798919, 2015). "This study aimed to assess MVRs in ESR1 in breast cancer cell lines, tumour biopsies and exfoliated epithelial cells from expressed breast milk (EBM), to determine their significance for ESR1 transcription." (PMID 25927974, 2015). "ESR1 has metastasis-suppressor properties, especially in breast cancer, suggesting a tumor-suppressor role (Issa, Ottaviano, Celano, Hamilton, & Davidson, 1994)." (PMID 27158284, 2015). "Applying this view to the ovarian and breast cancer portions of the network brought forward several marked nodes, one of which is the estrogen receptor ESR1." (PMID 25953855, 2015). "Third, SNAI2/SLUG is significantly inversely correlated with ESR1 expression and prognostic in analogy to breast cancer." (PMID 25928859, 2015). "A functional study of putative ESR1 target genes, regulated by either type I or type II TF binding sites, was carried out in breast cancer cell line MCF-7 by using histone modification data, microarray gene expression profiles, and nucleosome density." (PMID 26099425, 2015). "Previous studies have shown that ER absence is a result of hypermethylation of CpG islands in the 5’ region of ER coding gene (ESR1) in a fraction of breast cancer." (PMID 26141719, 2015). "The molecular factors that define endocrine response in ESR1-positive breast cancer patients remain poorly understood." (PMID 26169690, 2015). "We assayed the level of ESR1 mRNA in all six human breast cancer cell lines in DAC-treated and control cells using RT-PCR." (PMID 25927974, 2015). "As expected, epithelial genes known to be inactivated during EMT in breast cancer cells, such as Cdh1 (E-cadherin), Ocln (Occludin), Epcam, Cldn7 (Claudin 7), Id1, Krt7, Esr1, Cav2, Dsp, Gata3, and Cadm1 were among the downregulated genes." (PMID 25674539, 2015). "Functional annotation of the three types of ESR1 target genes also suggests that, only 'A' genes are highly enriched in pathways of importance to breast cancer such as the MAPK signaling pathway." (PMID 26099425, 2015). "ESR1 and β-catenin have been found to precipitate within the same immune complexes in colon cancer and breast cancer." (PMID 26432349, 2015). "The ZNF365, ESR1, LSP1 and SGSM3 loci are also associated with breast cancer risk, implicating a shared genetic basis of mammographic density and breast cancer." (PMID 26275715, 2015). "Together these data indicate that the expression of ACOX2-i9 is effected by ESR1 stimulation and inhibition in breast cancer cell lines." (PMID 26183823, 2015). "Intriguingly, comparing ER+ preM and postM breast cancer, the most altered gene was ESR1 itself, an observation that has previously been reported." (PMID 26251034, 2015). "The miR-221/222 cluster has also been shown to induce EMT in breast cancer cells by targeting Dicer, ESR1 (estrogen receptor 1) and TRPS1 (trichorhinophalangeal syndrome type I)." (PMID 25614041, 2015). "Our findings fit into the consistent overall picture that a distinct subgroup of non-small cell lung cancer (ESR1 high expression tumors) has certain similarity and analogy to breast cancer, based on several epidemiologic and observational studies." (PMID 25928859, 2015). "Analogous to what is observed for ESR1 in breast carcinoma, SPIB 'A' genes show the highest gene expression in diffuse large B cell lymphoma, and the strongest response after silencing of SPIB by RNA interference in ABC DLBCL cell lines." (PMID 26099425, 2015). "This study suggests that silybin and silybinphosphatidylcholinedown regulate ESR1 inER+ breast cancers." (PMID 24611152, 2014).
breast cancer (continued). "We examined the effect of silybin and silybin-phosphatidylcholine on ESR1 expressionin T47D breast cancer cells by RT-PCR." (PMID 24611152, 2014). "Variants in or near the known breast cancer susceptibility loci TERT, ESR1 and 19p13.11 showed strong associations (P <10−6) with at least one of the categories in all subtype analyses in BRCA1 carriers." (PMID 25919761, 2014). "Examples are emerging, however, including targeting HER2 in HER2 mutant breast cancer and mutant ESR1 in ESR1 endocrine refractory luminal-type breast cancer." (PMID 25606588, 2014). "In breast cancer patients, the patterns of methylation of the ESR1 and 14-3-3-σ promoters were significantly different compared to healthy controls." (PMID 24748968, 2014). "Obviously, this result is consistent with our knowledge that the estradiol treatment significantly induces the activity of ESR1 in breast cancer cells." (PMID 24302579, 2014). "Regarding luminal breast cancer cells, miR-18 has been shown to inhibit cell proliferation by targeting ESR1." (PMID 25069832, 2014). "Among these SNPs, rs2046210, located between coiled-coil domain containing 170 (CCDC170, also called C6orf97) and estrogen receptor 1 (ESR1) at 6q25.1, was first reported to be associated with the risk of breast cancer in Chinese populations." (PMID 25116933, 2014). "Since the ESR1 gene is rarely amplified in breast cancer, ERαexpression is normally ascribed to a lineage choice that traps the cells in anERα + state." (PMID 25527189, 2014). "About 70% of human breast cancers express the estrogen receptor alpha (ERα,ESR1), but genetically defined tumors based ontransformation of normal human cells are usually ERα negative." (PMID 25527189, 2014). "Despite the importance of ERα in breast cancer diagnostics and therapy, our understanding of regulation of the ESR1 gene in ER+ cancer cells and by cancer therapeutics is limited due to its complex gene organization." (PMID 24339902, 2013). "This case–control study showed that rs2046210 and rs3757318 located near the ESR1 gene and rs3808662 located on TNRC9 are associated with breast cancer risk in Japanese women." (PMID 24289300, 2013). "Since our initial report of 36% copy number increase, numerous studies have either confirmed or challenged that ESR1 is frequently gained in breast cancer." (PMID 24367641, 2013). "Expression of ESR1 mRNA in breast cancer cells is controlled predominantly through a proximal promoter within ∼400 base pair (bp) of the transcription start site (TSS)." (PMID 24339902, 2013). "To this end, we have analyzed the occurrence of polymorphisms in three genes (ESR1, CYP2C19 and UGT2B15) that were earlier shown to have prognostic significance in tamoxifen-treated breast cancer patients." (PMID 23951298, 2013). "The proximal promoter is a major regulatory region governing ESR1 mRNA in breast cancer, and the distal enhancer is involved in regulation of ESR1 mRNA by estrogen." (PMID 24339902, 2013). "The H:I ratio, also known as Theros Breast Cancer index is a molecular grade index for ESR1-positive breast cancer patients treated with tamoxifen." (PMID 27605190, 2013). "Primary tumor samples from 281 stage I-III consecutive breast cancer patients were analyzed for ESR1 gene dosage using real-time PCR with locked nucleic acids hydrolysis probes." (PMID 23951298, 2013). "These clinical developments highlight the importance of understanding the control of ESR1 gene expression in breast cancer cells." (PMID 24339902, 2013). "We analysed ESR1 ChIP-seq data drawn from primary breast cancer samples in relation to GWAS disease/trait regions, DNase I hypersensitivity peaks and estradiol-induced gene expression." (PMID 24171864, 2013). "Prevalence of ESR1 amplification in breast cancer is highly disputed and discrepancies have been related to different technical protocols and different scoring approaches." (PMID 24367641, 2013).
breast cancer (continued). "In contrast, in the study of Nielsen including tamoxifen-treated patients, OS and DFS of breast cancer patients with ESR1 amplification were decreased." (PMID 23951298, 2013). "We hope that further validation of these results and an attempt to understand basic biological changes driven by increased ESR1 gene dosage as well as by ESR1 PvuII and UGT2B15*2 polymorphisms will contribute to the understanding of breast cancer biology." (PMID 23951298, 2013). "Large sections were taken from 24 high-grade breast cancers with ESR1 amplification according to pre-existing FISH results from a “classical” FISH assay and a differential qRT-PCR approach using SOD2 and ESR2 as reference genes." (PMID 24367641, 2013). "We evaluated 18 SNPs in 13 susceptibility genes/loci and identified 7 SNPs in 3 loci (ESR1, FGFR2, and TOX3) that were associated with breast cancer in the Chinese population." (PMID 24244489, 2013). "The studies presented here provide additional evidence for a functional role of the chromatin environment of the distal enhancer in controlling high levels of expression of ESR1 mRNA in ER-expressing breast cancer cells." (PMID 24339902, 2013). "Since most studies on ESR1 amplification included tamoxifen-treated groups, prognostic significance of ESR1 gene amplification in general population of breast cancer patients is unclear." (PMID 23951298, 2013). "Together, these data support the idea that ESR1 gene expression in breast cancer cells can be controlled via pharmacological targeting of distal regulatory elements." (PMID 24339902, 2013). "ESR1 amplification (with a cut-off level of 2.0) was found in 12% of the entire group of breast cancer patients, and in 18% of the ER-negative subgroup." (PMID 23951298, 2013). "Discrepant data have been published on the incidence and prognostic significance of ESR1 gene amplification in early breast cancer." (PMID 23923010, 2013). "Future targeting of ERα in breast cancer through the controlled expression of ESR1 mRNA will therefore be improved by broadening our understanding to include distal sites of regulation in addition to promoter analyses." (PMID 24339902, 2013). "A cross talk between the Estrogen Receptor (ESR1) and the Retinoblastoma (pRb) pathway has been demonstrated to influence the therapeutic response of breast cancer patients but the full mechanism remains poorly understood." (PMID 23900261, 2013). "A trend toward increased recurrence was also observed in tamoxifen-treated breast cancer patients carrying UGT2B15A allele and in patients with ESR1 PvuII vt allele." (PMID 23951298, 2013). "The aim of this study was to assess the prognostic role of ESR1 gene dosage in a consecutive group of breast cancer patients and to correlate this feature with clinico-pathological factors." (PMID 23951298, 2013). "This study aimed at assessing the prognostic role of ESR1 gene dosage in consecutive group of breast cancer patients and to correlate ESR1 gene dosage with their clinico-pathological data." (PMID 23951298, 2013). "In summary, we have showed that ESR1 amplification measured by real-time PCR with LNA probes is a poor prognostic factor in unselected breast cancer patients." (PMID 23951298, 2013). "Target genes of miR-206 are MET in RMS; estrogen receptor 1 (ESR1, alias; ERα) in breast cancer and EEC; and notch 3 (NOTCH3) in HeLa cells." (PMID 22308266, 2012). "This study provides strong evidence for a novel breast cancer susceptibility locus represented by rs9485372, near the TAB2 gene (6q25.1), and identifies two possible susceptibility loci located in the ESR1 gene and 11q24.3, respectively." (PMID 22383897, 2012). "Here we describe the use of the AQUA method of quantitative immunofluorescence (QIF) for measuring mRNA in situ using ESR1 (the estrogen receptor alpha gene) in breast cancer to determine its predictive value compared to Estrogen Receptor α (ER) protein." (PMID 22606272, 2012).